CD68 (CD68 molecule)
Diseases named in the same sentence as CD68 in open-access papers (continued):
Sharing a sentence is not in itself a finding about the gene and the disease.
cancer (continued). "Six hot spots in peritumoral tissue per patient were considered for the analysis i.e. areas most positive for CD68 examined at ×400 magnification to obtain the average value of the 6 areas around the cancer foci." (PMID 37435060, 2023). "The cell densities tended to be higher in the margins compared to the benign and cancer compartments, except for the CD68+ macrophages, which tended to be more abundant in the cancer compartment and the CD83+ dendritic cells in benign tissues (p > 0.05)." (PMID 37190147, 2023). "We have evaluated 16 studies that used macrophage/monocyte markers in PMDs and cancer using antibodies against CD68 (pan-MΦ), CD86, CD80 (both M1-MΦ), CD163 and CD204 (both M2-MΦ), and CD14 (monocyte/macrophage marker)." (PMID 37190121, 2023). "CD68+ macrophages also infiltrated less in the presence of high COMP expression by the cancer cells (p=0.033)." (PMID 37207219, 2023). "For instance, in several types of cancer, a higher CD68+ macrophage index is related to metastasis, a shorter time between relapses, a bad prognosis and a lower overall survival rate." (PMID 37345141, 2023). "For instance, the proportions (%) of CD68+ macrophages sequentially increase during the transition of normal mucosa into inflammatory hyperplasia and cancer in azoxymethane (AOM)-/DSS-induced model mice." (PMID 38633005, 2023). "HHI therapy appeared to upregulate MHC class I expression and increase infiltrating immune cells (CD8+, CD4+, HLA-DR-class II+ mononuclear cells, and CD68+ macrophages) at the cancer site." (PMID 37887561, 2023). "We stained stromal areas near cancer cells for panmacrophage (CD68), M2 macrophage (CD163), immune modification (PD-L1), and pancytokeratin (CK) markers using a multicolored immunohistochemical method." (PMID 36362023, 2022). "The proportion of positive area of CD56 (NK cells) and CD68 (macrophages) in GC tissues was significantly higher than that in cancer-adjacent tissues (CD56, Cancer vs. Cancer-adjacent, P < 0.0001; CD68, Cancer vs. Cancer-adjacent, P < 0.0001)." (PMID 35186032, 2022). "In summary, in this paper, we systematically discussed the aspects related to expression and mutant characteristics of CD68 in pan-cancer." (PMID 35550532, 2022). "Same conclusion derived from a cohort of 85 patients with prostate carcinoma from a Swedish study in which higher Gleason score correlates with increased density of CD68+ macrophages which also results as predictor of shorter cancer-specific survival (CSS)." (PMID 36338516, 2022). "In dogs, we found elevated immunostaining of CD68-macrophages in the lymph node of the aggressive cancer G3 and infiltrating CD20+-lymphocyte." (PMID 35222017, 2022). "The CD8+, CD3+, CD68+ T cells were mainly distributed in the cancer stroma, whereas the CD56+ T cells were mainly located in cancer nests." (PMID 35172862, 2022). "Recently, it was found that there were an increased number of podoplanin‐positive lymphatic vessels and CD68‐positive histiocytes in cancer patients treated with the radiotherapy." (PMID 36267823, 2022). "We then explored the relationship between CD68 expression and the number of neoantigens in human cancers." (PMID 35550532, 2022). "A small subset of CD8+, CD3+, CD68+ T cells were observed and were mainly distributed in the cancer stroma." (PMID 35172862, 2022). "In this study, we studied the expression of CD68 in 33 cancer types using large-scale RNA-sequencing (RNA-seq) data from The Cancer Genome Atlas (TCGA)." (PMID 35550532, 2022). "We then checked the mutant landscape of CD68 in different cancer types from the TCGA database using cBioportal." (PMID 35550532, 2022). "More studies focusing on the specific signaling pathways of CD68 in pan-cancer need to be conducted in the future." (PMID 35550532, 2022). "Next, we evaluated the correlation between the DNA methylation and mRNA expression of CLEC5A and immune-related gene (MRC1, CD163, CD8A, CD8B, CD68) in pan-cancer." (PMID 35979347, 2022).
cancer (continued). "Our results showed that CD68 was expressed in ML and Mo clusters in normal lung and cancer tissues; however, strongly expressed in AM clusters." (PMID 36077342, 2022). "Next, to understand the prognostic value of CD68 in pan-cancer further, we downloaded RNA-seq and clinical data of CD68 from the TCGA dataset." (PMID 35550532, 2022). "The relationship between CD68 expression and cancer prognosis, immune infiltration, checkpoint markers, and drug response was explored." (PMID 35550532, 2022). "In this study, we explored the role of CD68 in clinical outcome prediction and immune cell infiltration in pan-cancer from the TCGA and GETx databases." (PMID 35550532, 2022). "CD8, FoxP3, and CD68 markers were evaluated by immunohistochemistry in 258 carcinoma samples and positive cells were counted in stromal and intra-tumoral compartments." (PMID 35805132, 2022). "In HT-29 spheroids, the CD68+ macrophages were identified both in the necrotic core and among live cancer cells in the periphery." (PMID 34451433, 2021). "A large fraction of all interstitial cells tested CD68+ by signal-specific cell counting in both cancer (median 53.7% CD68+ cells) and cancer-free (median 35.6% CD68+ cells) individuals." (PMID 33723077, 2021). "Double-staining of CD68+/Rep+ cells was detected in 1.8% interstitial cells in cancer-free patients compared to 7.3% in cancer patients, which matches the values for Rep-positivity alone." (PMID 33723077, 2021). "Cancerous lesions had more infiltration of XBP1+CD68+ cells (white) compared to normal tissue (14.11 ± 1.10 vs. 3.40 ± 0.18; P < 0.0001), XBP1+CD206+ macrophages displayed the similar pattern (3.26 ± 0.37 vs. 1.07 ± 0.15; P < 0.0001)." (PMID 34667145, 2021). "Rep and CD68+ detection increased significantly in peritumor cancer tissues when compared to tissues of cancer-free individuals." (PMID 33723077, 2021). "A functionally relevant association with macrophages is deducted by quantification of Rep+ and CD68+ colocalization, underscoring significantly increased levels of specific macrophage populations in cancer over cancer-free samples." (PMID 33723077, 2021). "We used CD68 as a macrophage marker because it has classically been used to identify macrophages as a prognostic marker for cancer progression." (PMID 34045665, 2021). "Rep+/CD68+ double-positive cells in cancer-free individuals represent 4.8% of the total fraction of CD68+ cells, in contrast to 14,7% in cancer patients representing approximately a threefold increase." (PMID 33723077, 2021). "The ΔCt values of 11 cancer-related genes (HER2, ER, PR, BCL2, CEGP1, Ki67, STK15, STMY3, CD68, GSTM1, and BAG1) were positively associated with HDL." (PMID 34456877, 2021). "Additional immunofluorescence analyses were performed on HT-29 and MCF-7 spheroids, combining staining for CD68, CD11b, vimentin, and epithelial cell adhesion molecule (EpCam) to discriminate macrophages, fibroblasts, and cancer cells." (PMID 34451433, 2021). "When analyzing the spatial distribution on a single cell resolution, NKp46+ NKT cells and CD68+ macrophages were identified as being of particular importance when located in the direct vicinity of cancer cells." (PMID 33013928, 2020). "In the same cohort, increased density and cell profile area of CD68+ TAMs were recognized as predictors of shorter cancer-specific survival (CSS)." (PMID 33194645, 2020). "As reported by Silverberg, the percentage of PD-L1+CD68+ cells and PD-L1 expression were higher at the advanced stage of cancer (FIGO III-IV) than at the early stage (FIGO I-II) of disease." (PMID 33062717, 2020). "CD68, as reported in a previous study, provided a good predictive value as a prognostic marker for survival in cancer patients." (PMID 33104706, 2020).
cancer (continued). "Two main parameters are used to analyze the clinical significance of TAMs in human cancers—the amount of TAMs defined most frequently by CD68 expression and phenotype of macrophages, defined by different specific M1 and M2 markers." (PMID 33194645, 2020). "In contrast, only CD68 (macrophages) had significantly higher expression levels in the higher-TMB subtype than in the lower-TMB subtype of at least 6 cancer types." (PMID 30634925, 2019). "In OSCC stroma, CD31-positive cancer blood vessels, CD68- and CD11b-positive macrophages, and α-smooth muscle actin-positive cancer-associated fibroblasts partially expressed PTCH." (PMID 31744214, 2019). "CD68, a pan-macrophage marker, is most extensively used to detect TAMs; however, the expression of CD68 in cancer and stromal cells was found." (PMID 31799941, 2019). "The number of CD68-positive cells in the cancer stroma was significantly higher in ED type than in EX type." (PMID 31744214, 2019). "The number of macrophages that infiltrated the cancer stroma and expressed CD68 was significantly higher in ED-type stroma than in EX-type stroma." (PMID 31744214, 2019). "Insofar, in this study, we suggest TILs and CD68+ TAMs to be reliable cancer biomarkers prognosticating survival and outcome of HCC patients after surgery." (PMID 31170995, 2019). "In both ED and EX type, accumulation of CD68-positive round or dendritic-shaped cells was observed in the cancer stroma." (PMID 31744214, 2019). "The infiltration of macrophages in the TNBC specimen was higher than that in the nTNBC specimen, and the IHC score of CD68 was different significantly (P<0.001) between the two cancer types." (PMID 31853223, 2019). "Further, we processed the data according to different cancer stages and found an increased trend of pre-miR-100 expression in CD68+ cells along with cancer development." (PMID 30563983, 2018). "Chromogenic double staining with CD80 and CD68 in primary OSCC samples revealed centered distribution of M1-like macrophages in CD68+ clusters among the cancer nests." (PMID 29986759, 2018). "Across cancer types, percentages of single positive CD68+ and CD163+ pixels, ranged from 6.5 to 62.7%, while CD11b+ and CD11c+ single pixels ranged from 0.65 to 11%." (PMID 30619287, 2018). "In hepatocellular carcinoma, CD68(+) HLA-DR(+) M1-like TAMs were shown to suppress anti-tumor immunity and promote cancer metastasis through expression of B7-H1." (PMID 29986759, 2018). "An alternative marker commonly used to distinguish human macrophages is CD68, however, since CD68 can also be expressed by some stromal and cancer cells, particular care should be taken when using this marker to identify TAMs." (PMID 29594035, 2018). "In all, 35/104 of cancer tissues showed relative higher expression of C9 in TAMs (C9+/CD68+ ≥10%) compared with the others (C9+/CD68+ <10%)." (PMID 29900010, 2018). "The immune cell infiltration into the cancer tissue included increased numbers of macrophages (CD68+), helper T cells (CD4+), and CD25+ lymphocytes compared to benign tissue." (PMID 28794686, 2017). "Strong MUC2 expression and low IL-6 and CD68 expression were detected in the same specimen from a patient with stage IIA cancer (upper left and upper right)." (PMID 28725043, 2017). "In a multivariate analysis of MIBCs, a high count of CD68+ TAM was correlated with high T category, high-grade cancer, and higher risk of cancer-specific death when adjusted for CD3." (PMID 29048388, 2017). "A correlation between the IL-6 secretion of CD68 macrophages and a higher level of IL-6 in cancer cells was observed." (PMID 28725043, 2017). "CD68+ cells were located in the cancer stroma, while there was little co-localization of CD68+ and CCL18+ staining in OSCC tissues." (PMID 26919103, 2016). "The cancer tissue samples had increased CD68+ cells as well as increased M2 macrophage activation compared to the non-cancerous tissues." (PMID 26964534, 2016).
cancer (continued). "It was observed that the GFP+ cells isolated from ascites and solid tumors exhibited unlimited proliferative potential; the monoclonal cells were mouse-original, had a cancer cell phenotype and expressed the macrophage marker protein CD68." (PMID 25483261, 2015). "Immunostaining for the macrophage marker CD68 showed that these cancer tissues contained a large number of infiltrating macrophages." (PMID 24737780, 2014). "Immunohistochemical stainings for specific cell markers, such as CKs for cancer cells and CD68 for macrophages (double staining) and α-SMA for myofibroblasts were in addition performed on adjacent sections." (PMID 24889870, 2014). "In most cancers, TAMs express the M2-like phenotype, while CD68 is expressed in both M1 or M2 macrophages." (PMID 24489836, 2014). "The positive expression rates of CD163+ and CD68+ were 68% and 78% respectively in cancer tissues compared to 4% and 6% in the adjacent cancer tissues." (PMID 25144454, 2014). "The densities of CD68+ cells in the cancer tissues from the high MUC2 expression group and the low MUC2 expression group were similar (27.3±13.6 mm-2 vs. 26.0±11.9 mm-2); and no statistical significance was established (p=0.654, Student’s t test)." (PMID 24324582, 2013). "Increased infiltration of CD68+ macrophages and more cancer cells displaying EMT features were found in NTS+IL-8+ samples." (PMID 23418512, 2013). "Upon examining the cancer tissue sections, we observed that the intra-islet density of M1-polarized TAMs (CD68+ HLA-DR+ or CD68+ iNOS+) was significantly lower in the high MUC2 expression group than in the low MUC2 expression group (p<0.01, Student’s t test)." (PMID 24324582, 2013). "We found that most of the TAMs, which were closely surrounded by MUC2+ cancer cells, exhibited upregulated COX-2 expression (i.e., an increased ratio of CD68+COX-2+ cells/total CD68+ cells in the cancer islets)." (PMID 24324582, 2013). "A number of CD68-COX-2+ cancer cells were observed surrounding the CD68-COX-2+ TAMs, particularly in the specimens from the high MUC2 expression group." (PMID 24324582, 2013). "Increased infiltration of CD68+ TAMs and higher number of cancer cells displaying EMT-related features were found in NTS+IL-8+ samples." (PMID 23418512, 2013). "This expression has been referred to CD68 + cells, identified as macrophages predominantly found in cancer tissues." (PMID 24551805, 2013). "From these clusters, five major cell types were identified via classical cell markers, including T cells (CD3E, CD8A, CD3D), B cells (CD19, MS4A1, CD79A), myeloid cells (CD14, CD68, LYZ), endothelial cells (PECAM1, VWF, CDH5) and cancer-associated fibroblasts (CAFs) (ACTA2, FAP, PDGFRB)." (PMID 39941131, 2025). "In our previous studies, tissues adjacent to early- and late-stage dysplasia, which in >90% of cases precede CRC tumors, were already found to show significantly increased levels of Rep+CD68+CD163+ MPs when compared to mucosal tissues of cancer-free individuals." (PMID 40136704, 2025). "While a growing body of evidence supports the adverse prognostic role of CD68+ macrophages in many cancer types, the identification of different macrophage subpopulations in human tissues remains controversial because of the intrinsic limitations of surface marker-based analyses." (PMID 40112045, 2025). "Furthermore, mIHC staining was applied to evaluate the co-localization of CAF(SMA), macrophage (CD68), and malignant tumor cells (CK19), which was confirmed tightly adjunct with each other." (PMID 40303408, 2025). "Differential analysis between high-risk and low-risk cancer cells revealed that high-risk cancer cells exhibited elevated expression of genes associated with M2 macrophages, including CXCL2, IL6R, CXCL8, GDF15, CD68, and PTX3." (PMID 41034991, 2025). "The expression of CD68 is elevated in assorted types of cancer." (PMID 38357542, 2024).
cancer (continued). "If BMMFs contribute to cancer‐promoting chronic inflammation by direct or indirect interaction with Mfs, a correlation between Rep and CD68 Mf detection levels could exist." (PMID 36811271, 2024). "We analyzed cancer tissue samples from 79 NSCLC patients using multiplex fluorescence (mIF) staining to visualize various SHP-2+ TAM subpopulations (CD68+SHP2+, CD68+CD86+, CD68 + 206+, CD68+ CD86+SHP2+, CD68+ CD206+SHP2+) and T cells (CD8+ Granzyme B +) of immune cells." (PMID 38799432, 2024). "Thus, the role of CD68 in cancer is intricate and context-dependent, and further studies are needed to fully understand its function in assorted types of cancer." (PMID 38357542, 2024). "Immunohistochemical stains, such as CD68 for histiocytes, can aid in distinguishing GP from PCa, especially in florid cases where epithelioid histiocytes may mimic high-grade carcinoma." (PMID 39439619, 2024). "The cells were further annotated as specific cell type subpopulations according to the expression of classic markers, including T cells (CD3D+), myeloid cells (CD68+), endothelial cells (CD34+), hepatocytes (ALB+), B cells (CD79A+), and cancer-associated fibroblasts (CAFs) (ACTA2+)." (PMID 37383234, 2023). "However, there are few studies on the role of CD155 in relation to CD68 in malignant tumors, especially GAC." (PMID 37441080, 2023). "Furthermore, CD68+ macrophages (p = 0.036 for margins and p < 0.001 for cancer) and FoxP3+ regulatory T lymphocytes (p < 0.001 for both) were typically less abundant in the IDC-P compared to margins and cancer." (PMID 37190147, 2023). "In addition, we analyzed the related functional signaling pathways of CD68 through GSEA based on KEGG and HALLMARK databases in pan-cancer." (PMID 35550532, 2022). "CD68 levels were found to be elevated in many cancer types and showed significant prognostic value." (PMID 35550532, 2022). "Moreover, the relationship between the expression levels of CD68 and the infiltration of immune cells in the pan-cancer microenvironment was observed." (PMID 35550532, 2022). "Our study explored the majority of pathways related to the expression of CD68 in pan-cancer, which might help determine the exact function of CD68 and downstream signaling pathways in the future." (PMID 35550532, 2022). "Moreover, the upregulated expression of CD68 was closely related to the stromal, immune, and estimated scores in many types of human cancers." (PMID 35550532, 2022). "Furthermore, in this study, CD68 expression was found to be negatively correlated with DNA mismatch repair (MMR) markers in most types of cancer." (PMID 35550532, 2022). "Multicenter clinical trials that focus on the efficacy, safety, or risk benefit ratio of small molecules and predicted drugs might benefit patients with elevated CD68 in these cancer tissues." (PMID 35550532, 2022). "In cancer, CD68+ macrophages located around the tumor core contributed to the EMT process by triggering the downregulation of E-cadherin and the upregulation of vimentin, N-cadherin, and Snail in the epithelial and cancer cells via the release of TGF-β, a process potentially present in IPF as well." (PMID 36232756, 2022). "Cancer diagnostic TAM markers, CD68, CD204, CD206, and CD163, are expressed on lung tissue AM; however, the poor MAFB expression on AM might significantly impact the assessment of cancer progression using TAM as an indicator." (PMID 36077342, 2022). "We also discussed the value of CD68 in the prognostic prediction of pan-cancer." (PMID 35550532, 2022). "Thus, the DNA methylation differences of CLEC5A and immune-related gene (MRC1, CD163, CD8A, CD8B, CD68) between tumors and normal tissues in various cancers were evaluated with the GSCALite platform." (PMID 35979347, 2022). "The relation of CD8+ T cells to CD68+ macrophages remains the same in both carcinomas." (PMID 35463364, 2022).